Y_RNA (Y RNA )
Gene: Miscellaneous RNA gene on chromosome 9 (97,915,690 to 97,915,796, forward strand). Ensembl gene ENSG00000201830.
Homologues: Orthologues: chimpanzee Y_RNA (99% identical), macaque Y_RNA (93% identical). Paralogues in human: RNY1P5 (86% identical), Y_RNA (85% identical), Y_RNA (84% identical), RNY1 (83% identical), Y_RNA (83% identical), Y_RNA (82% identical), Y_RNA (81% identical), RNY1P11 (80% identical), Y_RNA (80% identical), Y_RNA (79% identical), RNY1P1 (78% identical), RNY1P13 (78% identical), and 94 more.